CFTR (CF transmembrane conductance regulator)
Diseases named in the same sentence as CFTR in open-access papers (continued):
Sharing a sentence is not in itself a finding about the gene and the disease.
cystic fibrosis (continued). "The extent of cystic fibrosis manifestations is directly correlated with the CFTR genotype." (PMID 37893045, 2023). "However, the management of cystic fibrosis has made significant progress in recent years with the emergence of CFTR modulators, which aim to partially restore the functionality of the CFTR protein." (PMID 37063653, 2023). "In cystic fibrosis, certain N-terminal PTCs (such as E60X, L88X) result in the production of partially functional cystic fibrosis transmembrane conductance regulator (CFTR) proteins due to downstream translation initiation." (PMID 37047074, 2023). "Additionally, TNFα and IL-17-induced RANKL production in osteoblast from cystic fibrosis patients was reverted via treatment with a CFTR modulator." (PMID 36979360, 2023). "Furthermore, a pivotal study described the CRISPR-Cas9-mediated correction of the F508 deletion in the CFTR gene in adult intestinal stem cells derived from cystic fibrosis patients." (PMID 36959902, 2023). "Lack of expression or dysfunctional CFTR in IC-B cells leads to loss of HCO3- secretion in the collecting duct which explains metabolic alkalosis observed in people with cystic fibrosis." (PMID 36866602, 2023). "The pulmonary ionocyte appears to be a major source of CFTR activity in the airway epithelium, suggesting a role in luminal pH regulation that could be relevant for cystic fibrosis physiopathology." (PMID 36901843, 2023). "The circumstance of poor water permeation arises in the disease condition of cystic fibrosis, where defects in the CFTR gene prevent chloride transport across the apical membrane of epithelial cells, and between cells via the paracellular route, thereby preventing water transport into the airways." (PMID 37529032, 2023). "Notably, we found ATP6V1G3+ ionocyte expansion in the intrapulmonary bronchial SMG ducts of CFTRG551D/G551D cystic fibrosis ferrets removed from treatment with a CFTR modulator (VX-770)." (PMID 37730992, 2023). "CF is an autosomal recessive condition that affects various organs and tissues, characterized by mutations of the Cystic Fibrosis Transmembrane conductance Regulator (CFTR) channel, a protein that regulates the exchange of chloride, bicarbonate, and sodium ions through epithelial membranes." (PMID 37175888, 2023). "Moreover, the divergent role of CFTR in ionocytes and secretory cells suggests that cystic fibrosis disrupts both liquid secretion and absorption." (PMID 37581935, 2023). "Furthermore, the panel used for the screen does not cover the entirety of each of the target genes responsible for cystic fibrosis (CFTR) or haemoglobinopathies (HBB)." (PMID 39698301, 2023). "CFTR-modulator therapy has been shown to improve lung function, exacerbation rate, body mass index, quality of life and other aspects of life of patients with cystic fibrosis." (PMID 36738326, 2023). "We thank Cystic Fibrosis Foundation for gifting us with the CFTR correctors." (PMID 37561577, 2023). "In addition, the dysfunctional complex of phosphatase and tensin homolog deleted on chromosome 10 (PTEN) with the cystic fibrosis transmembrane conductance regulator (CFTR), which is associated with the pathogenesis of cystic fibrosis, increases the production of succinate and IRG1-ITA." (PMID 37261340, 2023). "Within the realm of genetic puzzles, cystic fibrosis emerges as a fascinating multisystemic and chronic disease with an autosomal recessive pattern of inheritance, where pathogenic mutations in the cystic fibrosis transmembrane regulator (CFTR) gene on chromosome 7 (locus 7q.31) play a pivotal role." (PMID 37719614, 2023). "Furthermore, some studies have demonstrated that ivacaftor enhanced the antimicrobial capacity of immune cells in cystic fibrosis patients treated with this CFTR modulator)." (PMID 36979360, 2023). "Cystic fibrosis is characterized by CF transmembrane conductanceregulator (CFTR) dysfunction." (PMID 36380568, 2022).
cystic fibrosis (continued). "Cystic fibrosis is a progressive, lethal, autosomal recessive monogenic disease, caused by defects in a single gene, Cystic Fibrosis Transmembrane conductance Regulator (CFTR), which encodes for a chloride and bicarbonate channel expressed in several epithelia." (PMID 36430961, 2022). "△F508 CFTR interacted with at least 638 proteins, which forms a △F508 CFTR interactome, and remodeling the interactome could promote the rescue of cystic fibrosis development." (PMID 35280995, 2022). "However, few CFTR potentiators have been tested in the clinic and until recently only ivacaftor was approved for cystic fibrosis patient use." (PMID 34644413, 2022). "Cystic fibrosis is a multisystem disease caused by certain mutations causing defective or absent CF transmembrane conductance regulator (CFTR) protein, the main function of which is the transepithelial anions transport." (PMID 35624751, 2022). "The contribution of CFTR variants to male infertility has not yet been assessed in Jordan, moreover, the N1303K mutation and its association with cystic fibrosis have not been studied yet in the Jordanian population." (PMID 34190021, 2022). "For 8 months (from 24 October 2019 to 28 August 2020 with a 1.5-month break), the patient took the CFTR modulator tezacaftor/ivacaftor and ivacaftor (Symdeko®)—a pathogenetic drug for the treatment of cystic fibrosis in patients older than 12 years with the genotype F508del/F508del." (PMID 36286063, 2022). "Indeed, it is well known that Cystic Fibrosis drugs modulate the function of the CFTR protein, but the drug’s effectiveness depends on which CFTR mutation a patient carry." (PMID 36699015, 2022). "A study suggests that the gene CFTR, which works as a glucose-sensing negative regulator of glucagon secretion in a cell, could lead to glucose intolerance in cystic fibrosis and other kinds of diabetes." (PMID 35642195, 2022). "The gene encoding the dysfunctional mutant CFTR chloride channel (the genetic basis for cystic fibrosis) was “the first disease gene to be isolated without the use of previous cytogenic clues” during the inception of the human genome project." (PMID 35626748, 2022). "The definition of CFTR-related disorder (CFTR-RD) has been introduced to define clinical entities associated with CFTR dysfunction not fulfilling the diagnostic criteria of cystic fibrosis." (PMID 35627274, 2022). "However, it has been noted that muscarinic responses of fluid secretion are reduced in submucosal glands from patients with cystic fibrosis and a recent study demonstrated a crosstalk of CFTR and TMEM16A in CFBE cells." (PMID 35196991, 2022). "The peripheral protein quality control (periQC) system eliminates the conformationally defective cystic fibrosis transmembrane conductance regulator (CFTR), including ∆F508-CFTR, from the plasma membrane (PM) and limits the efficacy of pharmacological therapy for cystic fibrosis." (PMID 35355508, 2022). "Milder clinical course was described in 3 ADPKD patients with cystic fibrosis with mutation of gene encoding CFTR channel, as compared with siblings with ADPKD without cystic fibrosis." (PMID 35328738, 2022). "A biosensor containing F508del-CFTR immobilized in membrane-like lipid vesicles that resembles the F508del-CFTR environment in vivo and that has already allowed the successful validation of computational predictions in the field of cystic fibrosis was used." (PMID 36293130, 2022). "In this study, thePNA sequences PNA1, PNA2, and PNA3 were selected for their potentialas anti-miR therapeutics in the context of cystic fibrosis, an autosomalrecessive genetic disease deriving from misfunctioning of cystic fibrosistransmembrane conductance regulator (CFTR) protein." (PMID 34468123, 2022).
cystic fibrosis (continued). "We review Pubmed literature published from January 2012 to July 2022, using the keywords “cystic fibrosis”, “CFTR modulators”, “ivacaftor”, “lumacaftor”, “tezacaftor”, “elexacaftor”, “immune response”, “phagocytes”, “macrophages”, “monocytes”, “neutrophils”, and “inflammation”." (PMID 36293274, 2022). "Cystic fibrosis is an autosomal genetic disorder characterized by the dysfunction of the cystic fibrosis transmembrane conductance regulator (CFTR) protein, an ion channel transporting Cl− and HCO3− that is expressed in various tissues, notably in mucus-producing organs." (PMID 36142171, 2022). "Presently, CFTR medications are only used to treat cystic fibrosis; however, the revelation that pathological processes can drive “acquired” CFTR dysfunction has spurred interest in using CFTR medications outside of the cystic fibrosis patient population." (PMID 36462404, 2022). "The CF lung environment may influence how vitamin D is metabolized because of the cystic fibrosis transmembrane regulator (CFTR) mutation in bronchial cells, which decreases its ability to activate vitamin D locally, leading to impaired antibacterial activity due to chronic inflammation." (PMID 36117182, 2022). "Cystic fibrosis lung disease is the main cause of mortality and morbidity in patients with CF for whom the emergence of effective mucolytic, anti-infective and causal cystic fibrosis transmembrane conductance regulator (CFTR) modulating therapies has markedly increased disease prospects." (PMID 36687447, 2022). "Although smoking parents are more likely to have an unhealthy child, and smoking was proven to cause CFTR dysfunction that is involved in cystic fibrosis, no direct causality was linked between paternal smoking and cystic fibrosis in children." (PMID 36429771, 2022). "Although synthetic mRNAs are a promising area of research and restoring gene function in other disease contexts has been explored extensively, such as CFTR in cystic fibrosis, research into the use of synthetic mRNAs to restore TSGs is currently somewhat lacking." (PMID 36700046, 2022). "Recently, a second-generation corrector, tezacaftor, was developed for the treatment of cystic fibrosis based on the structure of a first-generation corrector, lumacaftor, demonstrating rescue of CFTR folding and function with better pharmacokinetic properties and fewer adverse effects." (PMID 35159129, 2022). "The most common genotypic variant of Cystic Fibrosis is a three base-pair deletion (delF508) in the cystic fibrosis transmembrane conductance regulator (CFTR) gene causing no expression of this channel on the cell’s surface." (PMID 35385514, 2022). "Mutations in CFTR cause misfolding and decreased or absent ion-channel function, resulting in the disease Cystic Fibrosis." (PMID 36499495, 2022). "This additional example of co‐potentiation supports the concept that combinations of CFTR potentiators might have additional therapeutic benefit in cystic fibrosis." (PMID 34644413, 2022). "In this study, two homozygous variants in the CFTR gene have been found in two different patients; N1303K and D1152H, none of the patients had cystic fibrosis." (PMID 34190021, 2022). "In the human genome, exceptionally long introns are found in genes with a wide variety of cellular and developmental functions, including genes with important roles in some diseases, e.g., dystrophin in DMD and cystic fibrosis transmembrane conductance regulator (CFTR) in cystic fibrosis." (PMID 34907472, 2022). "Organoids and monolayers from an individual homozygous for the cystic fibrosis-causing ΔF508 CFTR mutation had no apical expression of CFTR and minimal changes in transepithelial current and conductance with forskolin treatment." (PMID 35685290, 2022).
cystic fibrosis (continued). "Interim results from an ongoing phase 1/2 placebo-controlled trial in cystic fibrosis showed that nebulisation into the lungs of patients with cystic fibrosis once a week over 5 weeks of CFTR mRNA packaged into delivery vehicles based on lipids was safe and well tolerated." (PMID 34685773, 2021). "There are drugs either available or being developed for cystic fibrosis; ones that might improve CFTR function in individuals with reduced levels may be worth further investigation in ME/CFS patients whose levels are low." (PMID 33572894, 2021). "Although CF is a monogenic disorder, considerable phenotypic variability of lung disease is observed in patients with CF, even in those carrying the same mutations in the cystic fibrosis transmembrane conductance regulator (CFTR) gene or CFTR mutations with comparable functional consequences." (PMID 34070354, 2021). "Refinement of personalized treatment of cystic fibrosis with emerging medicines targeting the CF basic defect will likely benefit from biomarkers sensitive to detect improvement of cystic fibrosis transmembrane conductance regulator (CFTR) function in individual patients." (PMID 34066648, 2021). "Cystic fibrosis is a monogenic disease caused by the lack of function of the cystic fibrosis transmembrane conductance regulator protein (CFTR), an anion-permeable channel involved in fluid transport through epithelia." (PMID 33805545, 2021). "The discovery of CFTR gene mutations linked to cystic fibrosis was contemporaneous, but the chloride channel activity of the CFTR protein was not known yet." (PMID 34208776, 2021). "Indeed, early rAAV gene therapy constructs for cystic fibrosis relied on this activity to drive expression of the CFTR (cystic fibrosis transmembrane conductance regulator) gene." (PMID 34785571, 2021). "Apart from these, there is a distinct spectrum of clinical manifestations, nonlethal, caused by mutations in the CFTR gene that cause CFTR protein dysfunction, but which do not meet the diagnostic criteria for cystic fibrosis, called CFTR-related disorders." (PMID 34945117, 2021). "For example, there are over 1500 mutations to the CFTR gene associated with cystic fibrosis, although the role of each in creating disease is not clearly understood." (PMID 34534781, 2021). "Hence, these results lead to envisage the druggability by FC or its derivatives of the 14-3-3/CFTR complex as a new approach for cystic fibrosis therapeutics development." (PMID 34572605, 2021). "In addition to tau, Aha1 stabilizes other Hsp90 clients including mutant cystic fibrosis transmembrane conductance regulator, CFTR, which causes cystic fibrosis, and mutant melanocortin-4 receptor, another misfolded transmembrane protein." (PMID 33832539, 2021). "CF is a genetic disorder caused by the presence of mutations in the CFTR gene encoding for a protein called cystic fibrosis transmembrane conductance regulator (CFTR), a cell-surface localized chloride channel that regulates absorption and secretion of salt and water across epithelia." (PMID 34835383, 2021). "List of ncRNAs that directly or indirectly target and regulate CFTR in cystic fibrosis." (PMID 34819948, 2021). "We review PubMed literature published from April 2016 to May 2021, using the keywords “cystic fibrosis”, “CFTR modulators”, and “combination therapy”." (PMID 34577628, 2021). "List of ncRNAs and their targets (other than CFTR) and functions in cystic fibrosis." (PMID 34819948, 2021). "In addition, most individuals with cystic fibrosis, a genetic disorder caused by mutations of the cystic fibrosis transmembrane conductance regulator (CFTR) gene, are colonized by P. aeruginosa, which is a major cause of morbidity and mortality in these patients." (PMID 34660345, 2021). "The development of CFTR modulators is changing the natural history of cystic fibrosis." (PMID 34356748, 2021).
cystic fibrosis (continued). "For instance, the ClC-2 chloride channel, which might compensate for the malfunction of CFTR in absorptive epithelia during cystic fibrosis, contains a dileucine motif." (PMID 34234241, 2021). "The most recent report of PTC suppression demonstrates the use of sup‐tRNAs for cystic fibrosis to restore full‐length cystic fibrosis transmembrane conductance regulator (CFTR) protein and restoration of PTC reporter activity in eukaryotic cells and mouse skeletal muscle." (PMID 33567469, 2021). "ASL pH is regulated by various mechanisms involving paracellular pathways and membrane transport proteins, among which, Cystic Fibrosis Transmembrane Conductance Regulator (CFTR—also known as ABCC7) has received emphasis as the genetic defect behind Cystic Fibrosis." (PMID 33568708, 2021). "On a large scale, the identification of CREs and a better understanding of the CFTR gene regulatory mechanisms could explain the phenotypic variability, and be promising therapeutic targets in cystic fibrosis and its related disorders." (PMID 33807548, 2021). "According to a study on cystic fibrosis, which is an inherited disorder and affects the lung, intestine, pancreas, and livers, hepatic Sult1e1 activity was increased in cystic fibrosis transmembrane conductance regulator (CFTR) −/− mice compared with CFTR+/+." (PMID 34539442, 2021). "An in-depth understanding of intracellular processes involved in CFTR impairment may reveal novel opportunities in pharmacological agents of cystic fibrosis." (PMID 34832033, 2021). "Studies on cystic fibrosis indicate, however, that not all CFTR variants are correlated with pancreas insufficiency." (PMID 34065437, 2021). "Ultimately, nanoparticles (see Vectors section) combined with the SB transposon system have provided expression of Factor VIII for 50 weeks in hemophilia A mice and long-term cystic fibrosis transmembrane conductance regulator (CFTR) transgene expression in the lungs of cystic fibrosis mice." (PMID 34064900, 2021). "Therefore, iPSC organoids provide a robust functional assay for CFTR gene and facilitate personalized medicine development for cystic fibrosis." (PMID 33900491, 2021). "Cystic fibrosis is a multi-system disease affecting organs and tissues wherein CFTR is expressed." (PMID 34685773, 2021). "Expanding the understanding of how airway inflammation improves CFTR rescue may benefit cystic fibrosis patients." (PMID 34831482, 2021). "A few classical disease-causing examples of this type include missense mutations in Aquaporin-2, cystic fibrosis transmembrane conductance regulator (CFTR), and insulin receptor, which lead to nephrogenic diabetes insipidus, cystic fibrosis and diabetes mellitus, respectively." (PMID 34359917, 2021). "Therefore, we have chosen to carry out complete CFTR analysis in both members of the couples in the event of prenatal ultrasound suspicion of cystic fibrosis." (PMID 33946859, 2021). "CFTR availability is reduced with defects in CFTR genes (i.e., cystic fibrosis)." (PMID 32124007, 2020). "This practice allows the identification of the additional CF-causing variants that are not included in the predefined panel and to identify infants with the CFTR-related metabolic syndrome, also known as Cystic Fibrosis Screen Positive, Inconclusive Diagnosis, which requires medical attention." (PMID 33124618, 2020). "Cystic fibrosis is an autosomal recessive genetic disorder that leads to functional impairment in the cystic fibrosis transmembrane conductance regulator (CFTR) channel, leading to impaired mucociliary transport, recurrent infections, airflow obstruction, bronchiectasis, and altered gas exchange." (PMID 32078644, 2020). "On the other hand, defective CFTR function further impaired autophagy in cystic fibrosis patients." (PMID 32724454, 2020). "Male infertility also occurs in cystic fibrosis and the congenital bilateral absence of the vas deferens, both caused by mutations in the CFTR gene, located on chromosome 7." (PMID 32722328, 2020).